AHR (aryl hydrocarbon receptor)
Diseases named in the same sentence as AHR in open-access papers (continued):
Sharing a sentence is not in itself a finding about the gene and the disease.
tumor (continued). "The differential effects and distinct molecular pathways associated with AHR and ELAVL1 modulation highlight their potential as therapeutic targets for PDAC treatment, particularly in overcoming chemoresistance and inhibiting tumour progression." (PMID 37685961, 2023). "This has been most frequently shown to be the case in the tumor microenvironment, where tumor-released kynurenine activates the AhR on NK cells and CD8+ T cells to induce a state of ‘exhaustion’ in these tumor-killing cells." (PMID 37174637, 2023). "Studies have demonstrated a critical role of TDO2/Kyn/AHR pathway activation in the promotion of tumor growth." (PMID 37607000, 2023). "Initially, we offer our readers a brief discussion about the oncogenic and tumor-suppressive roles of AhR specifically in the animal model studies." (PMID 37830596, 2023). "The protective role of AhR in tumorigenesis has been shown through the transcriptional regulation of tumor suppressor genes that reduce tumor burdens in mouse models of multiple tumor types, suggesting a paradoxical role of AhR in carcinogenesis." (PMID 37958428, 2023). "Since both CEBP-β and AhR are shown to drive tumor progression, these findings provide important additional pathways that can be affected by adipocyte-derived CM." (PMID 37447165, 2023). "In the transformed or cancer cells, in contract, AHR is tumor suppressive through its negative regulation on signaling pathways of TGFβ, Nrf2, and other oncogenes." (PMID 37151890, 2023). "What can be understood that already in early stages of tumor development, the balance of gut microbiota is altered possibly contributing to the observed shift toward higher frequencies of AhR." (PMID 37781044, 2023). "Similar findings of IFN-activated cytoplasmic transcription factor AhR were also observed in tumor cells." (PMID 37256962, 2023). "This assumption can be supported by chemo drug killing of tumor cells, which commonly increases AHR expression." (PMID 38099490, 2023). "Tumor expression of AHR can result in an autocrine AHR-IL-6/STAT3 signaling loop via kynurenine, an immunosuppressive AHR agonist ligand produced by the metabolism of the essential amino acid tryptophan." (PMID 37511453, 2023). "Because AhR can be regulated by small molecules, the AhR has been suggested to be an attractive target for the tumor microenvironment and immunotherapy to treat cancer." (PMID 37696458, 2023). "The pro-tumor activity is consistent with the increased kynurenine activating AHR and enhancing immune tolerance." (PMID 37296860, 2023). "The intent of this review was to synthesize the evidence supporting AhR-dependent tumor suppression and distill insights for development of AhR-targeted cancer therapeutics." (PMID 37106727, 2023). "AhR regulates the expression of cytochromes P450, which are the major enzymes responsible for tumor formation, metastasis, and prevention." (PMID 38068712, 2023). "Despite both pro- and anti-tumorigenic activities of AHR had been uncovered in a wide spectrum of experimentations or clinical observations it is difficulty at the present to characterize when and how AHR is oncogenic or tumor suppressive." (PMID 37151890, 2023). "The induction of the IDO1-Kyn-AhR axis by p27 prevents IFN-γ-induced STAT1 signaling-mediated tumor cell apoptosis and activates the dormancy program in TRCs." (PMID 37380989, 2023). "The kynurenine pathway, IDO, and AHR pathway have gained significant attention in cancer research due to their potential roles in tumour progression and immune regulation." (PMID 37760608, 2023). "I3P derivatives derived from the gut microbiota seemingly override their endogenous counterparts in activating AHR, thus enhancing tumor growth, suggesting the existence of a greater abundance of microbiota-derived AHR ligands in the TME96." (PMID 37394584, 2023). "In other words, AhR expression is abundant in human tumor cells and closely related to the immune system and function." (PMID 38053135, 2023).
tumor (continued). "To investigate the CRC-suppressing effect of AhR in vivo, we subcutaneously transplanted DLD-1/AhR-/- cells into Balb/c nude mice, finding that knockdown AhR suppressed tumor growth." (PMID 37781044, 2023). "The development of AhR-targeted anticancer agents requires a thorough understanding of the molecular mechanisms driving tumor suppression." (PMID 37106727, 2023). "The function of the ligands (AHR agonist or antagonist), tumor type and the cellular and protein environment all influence the relationship between AHR and tumor." (PMID 37179416, 2023). "Recent studies have shown that KYN and KYNA are endogenous AhR agonists, whose activation induces the differentiation of Treg cells and an immune tolerance response, preventing the elimination of tumor cells." (PMID 36986469, 2023). "Both kynurenine and IDO1 are confirmed as important regulators for body immune homeostasis.And AHR, an important sensor for bacterial indoles and kynurenine, also plays pivotal roles bacterial mediated tumor immune microenvironment." (PMID 36927689, 2023). "The AhR either suppresses clonogenic potential or augments differentiation of cancer stem cells (CSCs) to exert tumor suppressor activities." (PMID 37241719, 2023). "The percentage and number of CD4+ and CD8+ T cells within tumor-draining lymph nodes returned back to the baseline levels after clearance of the tumors in AhR-silenced-MOC1-implanted mice." (PMID 37830596, 2023). "AhR activation by the IDO1/TDO2 product kynurenine promotes a tumor microenvironment that is defective in recognition and eradication of the cancer cells." (PMID 37830596, 2023). "Activation of AhR on the tumour by KYN induces an inflammatory positive autocrine feedback loop (IDO1-AhR-IL-6-STAT3 signalling pathway) to enhance tumour growth." (PMID 37041200, 2023). "Are the AhR interactions with NF-kB and the melatonergic pathway relevant to variations in macrophage phenotype induction in the tumor microenvironment?" (PMID 36613754, 2022). "This appears to be clever dual manoeuvring by tumours to simultaneously maximise AhR activation and undermine T-cell immunity." (PMID 36286592, 2022). "AhR would serve as a limiting factor in the control of both senescence and pluripotency, eventually restricting tumor development with age." (PMID 35619220, 2022). "AHR was a ligand activated transcription factor known for its tumor-promoting effects, and uremic toxins derived from intestinal microbiota have been recognized as effective endogenous ligands for AHR activation." (PMID 35663394, 2022). "There exist an interplay between tumor cells and the host microbiota that produce AhR agonists from dietary sources." (PMID 35173722, 2022). "ITE is an AhR (aryl hydrocarbon receptor) ligand; the AhR can inhibit cellular proliferation in a ligand-dependent manner and act as a tumor suppressor." (PMID 35155672, 2022). "Convergent results obtained by Opitz and colleagues revealed that tumors expressing TDO degrade tryptophan in kynurenine, which suppresses an anti-tumor immune response through the AHR axis." (PMID 36188218, 2022). "Collectively, the body of literature indicates that the role of AhR in cancer is complex, with ample evidence for both an oncogenic and tumor suppressor function, depending on cell and tissue context and mode of AhR activation." (PMID 36588678, 2022). "Potential links between the AhR and the control of tumor cell proliferation and metabolism thus deserve more attention." (PMID 36077780, 2022). "The mutually antagonistic interactions of melatonin and the AhR are an important aspect of the intercellular interactions occurring in the tumor microenvironment." (PMID 36613754, 2022).
tumor (continued). "Clearly, the interactions of melatonergic pathway regulation with AhR effects requires investigation in macrophages of the tumor microenvironment." (PMID 36613754, 2022). "Aryl hydrocarbon receptor (AhR), a member of the basic helix-loop-helix transcription factor family, is best known for mediating the toxicity and tumor-promoting properties of the carcinogen 2,3,7,8-tetrachlorodibenzo-p-dioxin (TCDD)." (PMID 35773697, 2022). "Recently, AhR antagonist exhibited anti-tumor efficacy alone and increased the activity of PD-L1 blockade in various syngeneic mouse tumor models." (PMID 35173722, 2022). "Aryl hydrocarbon receptor (AHR) is expressed by immune cells, epithelial cells, and some tumor cells." (PMID 36483296, 2022). "IL4I1, a metabolic immune checkpoint that activates the aryl hydrocarbon receptor (AHR) through the generation of indole metabolites and kynurenic acid, has been shown to promote cancer cell mobility and metastasis and to suppress anti-tumor immunity." (PMID 36216799, 2022). "One of the most intriguing features of AHR is that its role in both oncogenesis and stemness is conditioned by the cell type, acting as a tumor suppressor or as an oncogene upon specific cell types, tissues or organs." (PMID 35465323, 2022). "In summary, data from the literature strongly suggest AhR’s critical role in the microenvironment of mammary tumorigenesis promoting tumor progression and metastasis." (PMID 36588678, 2022). "Does tumor-derived kynurenine drive platelet AhR/CYP1B1 to increase the NAS/melatonin ratio, with the autocrine effects of NAS activating the truncated TrkB-T, leading to platelet release of pro-inflammatory cytokines and pro-angiogenic factors ?" (PMID 36613754, 2022). "(ii) AhR Function: In many tumor types, the AhR alone exhibits tumor promoter or tumor suppressor like activity, and this can be observed in animals or cells after knockdown or overexpression studies." (PMID 36428667, 2022). "The choice to include AhR agonists or antagonists in therapies needs to be based on its exact functions in each tumor type and likely in each tumor subtype." (PMID 35681770, 2022). "In the tumor microenvironment, the activation of AHR induces immune tolerance of dendritic cells and promotes the differentiation and proliferation of regulatory T cells, leading to tumor immune escape and malignant proliferation." (PMID 36266304, 2022). "Intratumoral Fn injection led to an increase of formate levels within tumour interstital fluids (TIFs), accompanied by an increased AHR, CYP1B1, SOX2 and ALDH1A1 (trendwise) gene expression." (PMID 35437333, 2022). "AhR inhibitors have been shown in preclinical studies to reverse IDO/TDO-mediated tumour progression and to improve the efficacy of PD-1 blockade." (PMID 36286592, 2022). "As the tumor benefits from the BDNF-mimicking effects of NAS, factors that increase the NAS/melatonin ratio, including the AhR, P2Y1r and mGluR5 become other direct and indirect targets of the tumor in its quest for survival." (PMID 36613754, 2022). "It has been shown that treatment of head and neck squamous cell carcinoma with the antagonists of AhR decreased the migration and invasion of these tumor cells." (PMID 35773697, 2022). "The role of the AhR in human cancer remains less clear, as in some tumor types, the AhR plays a role of a tumor suppressor, while in others, it behaves as an oncogenic factor." (PMID 36077780, 2022). "AHRR is a putative tumor suppressor and regulates the activity of AHR, while NCOA2 functions as a transcriptional coactivator for nuclear hormone receptors." (PMID 35832542, 2022). "In the liver, secretion of MCP2/CCL8, a cytokine that chemoattracts monocytes and macrophages to damaged or tumor areas, was significantly higher in AhR−/− mice at 22 months compared to age-matched AhR+/+ mice." (PMID 35619220, 2022). "Thereby, suppression of AhR signals by directly targeting AhR or upstream ITO/TDO signals is expected to mediate tumor regression." (PMID 35831824, 2022).
tumor (continued). "As disparities between transcript levels and protein expression are common in tumor tissue, we decided to validate our finding by staining the tumor tissue for AhR protein and comparing the intensity of its staining with the adjacent normal colon mucosa." (PMID 36077780, 2022). "Amount of evidence suggest that IDO1- or TDO2-expressing tumor cells can escape immunosurveillance via Trp starvation, and AhR is involved in tumor immune evasion." (PMID 35173722, 2022). "As a deubiquitination, UCHL3 has been suggested to maintain cancer stem-like properties and accelerate tumor cell growth by stabilizing AhR protein." (PMID 35918714, 2022). "AHR is known for mediating the toxicity and tumor promoting properties despite the mechanism through which AHR activates carcinogenesis needing to be elucidated." (PMID 35935858, 2022). "ARNT is a protein shown to be involved in regulating tumor growth and angiogenesis along with its binding partner aryl hydrocarbon receptor (AHR)." (PMID 35197309, 2022). "Both Epacadostat and TCDD treatment led to activation of the AhR reporter, upregulation of IDO1 expression, and the nuclear translocation of AhR in both tumor cells and splenic T cells." (PMID 36163134, 2022). "It has been proven that kynurenine from tryptophan metabolism in cancer cells can induce the expression of FOXP3, a marker of regulatory T cells (Tregs), by activating the AhR nuclear transform to suppress tumor immunotherapy." (PMID 35571116, 2022). "Studies have shown that Kyn can reach concentrations sufficient to activate the AhR pathway in some tumor microenvironments." (PMID 35892593, 2022). "Indole-3-carboxylic acid, a microbial tryptophan metabolite, can enhance tumor malignancy and suppress antitumor immunity by activating aryl hydrocarbon receptor (AHR)." (PMID 35155234, 2022). "One intriguing feature of AHR is that its functions depend on the phenotype of the target cell, acting as a tumor suppressor or as an oncogene upon specific cell types, tissues or organs." (PMID 35465323, 2022). "Nonetheless, in the last decades, the kynurenine-AhR axis was shown to trigger tumor development in multiple ways." (PMID 35681770, 2022). "As noted, the AhR is an important target for tumor-derived kynurenine in the suppression of NK cell and CD8+ t cell activation." (PMID 36613754, 2022). "In preclinical models, enhanced activity of the kynurenine pathway (KP) has been correlated to failing of antitumor immunity and tumor progression which more likely relies on AhR activation." (PMID 35173722, 2022). "The AhR has been also reported to participate in the control of metabolic pathways, which contribute to the proliferation of tumor cells." (PMID 36077780, 2022). "KYN has also been shown to activate AhR in an autocrine/paracrine fashion, resulting in the suppression of antitumour immune responses and the promotion of tumour cell survival and motility." (PMID 35682980, 2022). "Using a melanoma model, it was shown that tumors expressing high levels of IDO1 present an enrichment of TAMs and selective inhibition of AhR decreases tumor progression, by inhibiting the immunosuppression mediated by IDO1." (PMID 36588678, 2022). "Compelling studies have demonstrated that the expression of AhR is tightly correlated to the drug’s resistance development in several tumor types." (PMID 35831824, 2022). "These miRNAs are also associated with the regulation of different cancers, as are the P2Y1r and mGluR5 receptors, whilst the AhR is a crucial aspect of cancers and the tumor microenvironment." (PMID 36613754, 2022). "Nonetheless, if AhR behaves as an oncoprotein in many tumors, it also displays tumor suppressive properties in other settings." (PMID 35681770, 2022). "AhR was present in tumor epithelial and stromal cells, including fibroblasts, endothelial and immune cells (such as lymphocytes)." (PMID 35203450, 2022).
tumor (continued). "TAMs play a role in inhibiting tumor growth and promoting the inhibition of anti-tumor immunity through AhR signaling." (PMID 35681736, 2022). "Lastly, the IDO1-kynurenine AhR axis upregulates PD1 expression in CD8 T cells providing an immune tolerant microenvironment for tumor cells." (PMID 35681770, 2022). "In tumor-infiltrating T cells, kynurenine binding to the aryl hydrocarbon receptor (AHR) regulates PD-1 expression by AHR binding to xenobiotic response element (XRE) motifs in the promoter region of PD-1." (PMID 35011741, 2022). "Here, we summarize the current knowledge about AHR’s role in skin carcinogenesis and focus on its impact on defense mechanisms, such as DNA repair, apoptosis and anti-tumor immune responses." (PMID 35311158, 2022). "Noteworthy, kynurenine was found to induce the generation of immunosuppressive Tregs in mice and certain tumor entities in patients in an AHR-dependent manner." (PMID 35311158, 2022). "New studies have shown that formate, as a gut-derived tumor metabolite associated with CRC progression, drives CRC tumor invasion by triggering the AhR signaling pathway, while increasing cancer stem cell potency and promoting CRC development." (PMID 36615706, 2022). "Together, their results suggest that tryptophan catabolism by TDO in tumors generates kynurenine, which activates the AHR pathway in adjacent cells through a paracrine fashion, contributing to tumor immune escape." (PMID 36188218, 2022). "Addressing other mediators of tumour activity related to Trp metabolism, notably activation of the AhR, IL-4I1, PARPs and SIRTs will be equally important, with AhR inhibition being a priority." (PMID 36286592, 2022). "Tumor cell release of kynurenine and its activation of the AhR is the most investigated aspect of how tumors act to regulate the mitochondrial melatonergic pathway in other cells of the tumor microenvironment." (PMID 36613754, 2022). "The activation of the first module through the production of kynurenine oncometabolites and the resulting activation of AhR has several consequences, including promoting tumor growth, immune evasion, metastatic spread and chemoresistance." (PMID 35681770, 2022). "We therefore propose that AhR is at the crossroad of signaling pathways that integrate stemness, senescence and tumor development during liver aging." (PMID 35619220, 2022). "Nowadays, attention has been focused on the effects of IDO1, because in addition to immune regulation, activation of the IDO1/Kyn/AHR axis affects tumor cell viability, proliferation, and apoptosis in vitro." (PMID 35371054, 2022). "The CCK8 analysis proved that Kyn promoted the proliferation of A549 and Lewis, whereas blockade of AhR signals by DMF suppressed the pro-tumor effects induced by Kyn." (PMID 35831824, 2022). "These metabolites, on the other hand, can promote tumor cell growth and limit immune cell activation through AhR and PXR receptors." (PMID 36612238, 2022). "Suchlike molecular mechanism is driven through the unbinding of transcription factor Sp1 from AHR promoter, suggesting an epigenetic mechanism for the control of AHR expression in human tumor cells." (PMID 36499247, 2022). "KYN has previously been shown to bind to and activate the AHR, providing another important link to the pro-tumor effects of IDO1." (PMID 35245456, 2022). "AhR is expressed at high levels in several tumours, and promotes immune tolerance by increasing the proportion of Treg cells (immunotolerant) at the expense of CD8+ T cells at least in human glioma." (PMID 36038791, 2022). "O-GlcNAcylation can significantly regulate cells and important transcription factors in the tumor microenvironment, including the AhR, YY1, the NLRP3 inflammasome, MDSCs, NK cells, and CD8+ t cells, as well as sirtuins and core metabolic processes." (PMID 36613754, 2022). "Altogether, the activation of AhR by Trp-derivative ligands mitigates the innate and adaptative immune responses to lend further support to tumor growth." (PMID 35173722, 2022).